CMTM3 (CKLF like MARVEL transmembrane domain containing 3)
Diseases named in the same sentence as CMTM3 in open-access papers (continued):
Sharing a sentence is not in itself a finding about the gene and the disease.
chordoma (3 papers, 2021 to 2024). Chordomas are rare malignant tumors arising from embryonic remnants of the notochord in axial skeleton. "Several recent studies (including our own) have revealed that EGFR-signaling dysbiosis modulated by CMTM3 and cMET exacerbated the chordoma process, and that DEPDC1B regulated ubiquitination of BIRC5 also promoted chordoma progression." (PMID 36248973, 2022). "In this study, the expression of CMTM3 was analyzed in eight paired chordoma tissues and their adjacent normal tissues by western blot." (PMID 34560882, 2021). "We subsequently employed a mouse model of chordomas to analyze the effects of CMTM3 in vivo by subcutaneously inoculating the flanks of NSG mice with U-CH1-MOCK cells or U-CH1-CMTM3 cells." (PMID 34560882, 2021). "We used adenovirus to overexpress CMTM3 in chordoma cell lines expressing relatively low levels of endogenous CMTM3 (JHC7 and U-CH1)." (PMID 34560882, 2021). "In this paper, we used CMTM3 overexpressed and CMTM3 silenced systems to explore the roles and mechanism of CMTM3 in chordomas." (PMID 34560882, 2021). "Although our findings demonstrate the roles and mechanism of CMTM3 in the tumorigenesis and development of chordomas, this study still has limitations." (PMID 34560882, 2021). "Taken together, CMTM3 suppresses chordomas metastasis via accelerating EGFR degradation and suppressing the EGFR/STAT3/EMT signaling pathway." (PMID 34560882, 2021). "This study investigates the function and mechanism of CMTM3 in chordomas and provides us with a potential target for the treatment of chordomas." (PMID 34560882, 2021). "Then, the expression of CMTM3 in chordoma JHC7, U-CH1, MUG-Chor1 cell lines was analyzed by Real-time PCR." (PMID 34560882, 2021). "We find that CMTM3 expression is reduced in chordoma tissues and inhibits proliferation, migration and invasion of chordoma cells in vitro and suppresses tumor growth in vivo." (PMID 34560882, 2021). "First, we find that CMTM3 is downregulated in chordoma tissues compared with the paired normal tissues." (PMID 34560882, 2021). "RNA-seq was performed to further explore the mechanism regulated by CMTM3 in chordoma cells." (PMID 34560882, 2021). "CMTM3 expression was significantly downregulated in the tumor tissues compared with the matched adjacent normal tissues at the protein level, which suggested that CMTM3 might play important roles in chordoma tumorigenesis and development." (PMID 34560882, 2021). "To identify whether CMTM3 participates in tumorigenesis, we analyzed the proliferation of chordoma cells." (PMID 34560882, 2021). "In summary, our study first shows the function and mechanism of CMTM3 in chordomas." (PMID 34560882, 2021). "Taken together, CMTM3 suppressed the migration and invasion of chordoma cells in vitro." (PMID 34560882, 2021). "The expression of CMTM3 in chordoma cell lines was tested by Real-time PCR and western blot." (PMID 34560882, 2021). "To illuminate the mechanism of the suppressive roles of CMTM3 in chordomas, we detected the expression of the epithelial specific junction protein E-cadherin and the mesenchymal proteins N-cadherin and Vimentin in CMTM3-overexpressed JHC7 and U-CH1 cells and CMTM3 silenced MUG-Chor1 and U-CH1 cells." (PMID 34560882, 2021). "CMTM3 expression was downregulated in chordoma tissues compared with paired normal tissues." (PMID 34560882, 2021). "CMTM3 might be a potential therapeutic target for chordomas." (PMID 34560882, 2021). "CMTM3 may act as a promising molecular target for chordomas, which would be clinically beneficial." (PMID 34560882, 2021).
chordoma (continued). "However, whether CMTM3 participates in the tumorigenesis and development of chordomas remain unknown." (PMID 34560882, 2021). "However, the roles and mechanism of CMTM3 in chordomas remain unknown." (PMID 34560882, 2021). "Primary chordoma tissues and the paired adjacent non-tumor tissues were collected to examine the expression of CMTM3 by western blot." (PMID 34560882, 2021). "In addition, we detected EGFR expression in CMTM3 overexpressed JHC7 and U-CH1 cells and CMTM3 silenced MUG-Chor1 cells by Real-time PCR and found that CMTM3 did not alter EGFR expression at the mRNA level, indicating CMTM3 might facilitate EGFR degradation in chordoma cells." (PMID 34560882, 2021).
glioblastoma (3 papers, 2016 to 2024). The most malignant astrocytic tumor (WHO grade IV). "In fact a previous study even indicated that higher CMTM1 and CMTM3 expression levels are significantly associated with shorter overall survival in glioblastoma." (PMID 31998718, 2019). "Therefore, it is necessary to verify whether CMTM3 is mutated in glioblastoma." (PMID 27121055, 2016). "Consequently, the study showed that CMTM1 and CMTM3 can be targets for treating glioblastoma." (PMID 38223763, 2024). "They found that CMTM3 is upregulated in glioblastoma tissues compared with non-neoplastic brain tissues and that knockdown of CMTM3 by siRNA reduces cell invasion." (PMID 27121055, 2016).
renal carcinoma (3 papers, 2014 to 2021). A carcinoma arising from the epithelium of the renal parenchyma or the renal pelvis. "It has recently been shown that CMTM3 was silenced or down-regulated in gastric, breast, and renal carcinomas 9-11." (PMID 34475993, 2021). "It has recently been shown that CMTM3 is silenced or down-regulated in gastric, breast, nasopharyngeal, esophageal, colon and renal carcinomas." (PMID 24586462, 2014).
seminoma (3 papers, 2014 to 2024). A radiosensitive malignant germ cell tumor found in the testis (especially undescended), and extragonadal sites (anterior mediastinum and pineal gland). "We also investigated the correlation between CMTM3 expressions in seminoma with pathological parameters, and noticed that decreased CMTM3 is significantly associated with advanced T stage." (PMID 24586462, 2014). "In a human seminoma cell line, upon the re-expression of CMTM3 via adenovirus delivery (Ad-CMTM3), the infected cells expressed a high level of p21, which led to arrest of the cell cycle at the G2 phase and inhibition of cell growth and migration." (PMID 38223763, 2024). "Reintroducing CMTM3 gene expression in a human seminoma cell line (NCCIT) by delivering an adenovirus (Ad-CMTM3) has been found to result in inhibition of cell growth and migration." (PMID 32944388, 2020).
colon carcinoma (2 papers, 2011 to 2020). "CMTM3 showed tumor-suppressive function while the DNA methylation of CMTM3 promoter inhibited CMTM3 expression in multiple tumors, such as gastric, breast, nasopharyngeal, male laryngeal, esophageal, and colon carcinomas." (PMID 33282744, 2020). "APC and CMTM3, EXO1 and HLTF are reported to be hyper-methylated in selected colon cancer samples." (PMID 22051105, 2011).
colorectal cancer (2 papers, 2019 to 2020). A primary or metastatic malignant neoplasm that affects the colon or rectum. "While DNA methylation in genes MDF1, SSTR2, CMTM3, TGFB2, and NDRG4 is a potential marker for the detection of colorectal cancer in the early stages of its development, hypermetylation in gene CLDN11 is associated with metastasis and poor prospect of patient survival with colorectal cancer." (PMID 32370233, 2020).
ovarian carcinoma (2 papers, 2019 to 2022). A malignant neoplasm originating from the surface ovarian epithelium. "Subsequently, analysis of the Oncomine database showed significant changes in the expression levels of CMTM3/7/8 mRNA in ovarian cancer tissues across multiple datasets." (PMID 36110202, 2022). "Among them, especially for ovarian cancer, CMTM3/4/6/7/8 had a relatively high expression in ovarian cancer compared to control normal tissues, while CMTM1/2/5 had a relatively low expression." (PMID 36110202, 2022).
acute respiratory distress syndrome (1 paper, 2025). Progressive and life-threatening pulmonary distress in the absence of an underlying pulmonary condition, usually following major trauma or surgery. "The mechanistic role of CMTM3 in acute respiratory distress syndrome (ARDS) is not known." (PMID 40196127, 2025).
endotoxemia (1 paper, 2024). "The population of peripheral blood neutrophils was significantly lower in Cmtm3 KO mice compared to WT mice in the LPS-induced endotoxemia model." (PMID 39455728, 2024). "The results showed that Cmtm3 KO reduced the pathological injury in the liver, lungs, and kidneys of LPS-induced endotoxemia mice, while TLR4 overexpression reversed this alleviating effect." (PMID 39455728, 2024). "Consistent with our findings in the CLP model, Cmtm3 KO resulted in a reduction of neutrophil infiltration in the liver, lung, and kidney tissues of mice with LPS-induced endotoxemia." (PMID 39455728, 2024). "Next, we validated the improvement of disease severity by Cmtm3 knockout through the TLR4 pathway in an LPS-induced endotoxemia model." (PMID 39455728, 2024). "Furthermore, CXCR2-specific antibodies prevented the release of BM neutrophils in both Cmtm3 WT mice and Cmtm3 KO mice in the LPS-induced endotoxemia model, as shown in." (PMID 39455728, 2024). "Cmtm3 KO alleviated the release of TNF-α, IL-1β, and IL-10 in the peripheral blood of LPS-induced endotoxemia mice, while TLR4 overexpression reversed this alleviating effect." (PMID 39455728, 2024). "Survival analysis indicated that Cmtm3 KO significantly improved the survival rate of LPS-induced endotoxemia mice, while TLR4 overexpression increased the mortality rate of Cmtm3 KO mice." (PMID 39455728, 2024).
gastritis (1 paper, 2023). Inflammation of the stomach. "CMTM3 expression was up-regulated in the H. pylori-infected gastritis sample compared to the uninfected ones." (PMID 36782312, 2023).
Obesity (1 paper, 2025). Accumulation of substantial excess body fat. "It provides evidence that CMTM3 has a significant role in adipogenesis and obesity, in addition to a tumor suppressor function in cancer." (PMID 40697995, 2025). "Our findings reveal a new biological function of CMTM3 in adipogenesis and shed light on its potential as a molecular target in obesity therapy." (PMID 40697995, 2025).
renal cell carcinoma (1 paper, 2016). "CMTM3 is also downregulated in 84% of renal cell carcinoma (63/75); Restoration of CMTM3 in a renal cell carcinoma cell line inhibits cell proliferation and migration; CMTM3 expression is significantly reduced in OSCC cell lines and primary tumor specimens." (PMID 27121055, 2016).
Sepsis (1 paper, 2024). Sepsis is defined as life-threatening organ dysfunction caused by a dysregulated host response to infection. "Remarkably, our investigation revealed that Cmtm3 deficiency resulted in a remarkable amelioration of sepsis survival rates, attenuation of inflammatory responses, and mitigation of tissue and organ damage in septic mice." (PMID 39455728, 2024). "Our findings suggest that targeting CMTM3 holds promise as a therapeutic approach to ameliorate the dysregulation of neutrophil migration and multi-organ damage associated with sepsis." (PMID 39455728, 2024). "Consequently, we employed a functional loss-of-function strategy, utilizing a systemic Cmtm3 knockout (KO) mice model, to elucidate the role of CMTM3 in the context of sepsis." (PMID 39455728, 2024). "Histopathological analysis of liver, lung, and kidney tissues using HE stains revealed that Cmtm3 KO reduced the pathological injury in these organs in CLP-induced sepsis mice, while TLR4 overexpression reversed this effect." (PMID 39455728, 2024). "This study shows that the membrane protein CMTM3 is upregulated in sepsis and critically regulates neutrophil migration, a key factor in sepsis progression." (PMID 39455728, 2024). "In this investigation, we identified CMTM3 as a potential contributor to the pathogenesis of sepsis." (PMID 39455728, 2024). "Survival analysis indicated that Cmtm3 KO significantly improved the survival rate of CLP-induced sepsis mice, whereas TLR4 overexpression increased the mortality rate of Cmtm3 KO mice." (PMID 39455728, 2024). "Future studies utilizing conditional knockout models are necessary to dissect the cell-type specific contributions of CMTM3, which will provide a clearer understanding of its role in sepsis." (PMID 39455728, 2024). "Using a Cmtm3 knockout mice model, we observed that the deletion of Cmtm3 ameliorates dysregulated neutrophil migration and reduces neutrophil infiltration in vital organs during sepsis." (PMID 39455728, 2024). "In order to investigate the function of CMTM3 in sepsis, we conducted further research using Cmtm3 KO mice." (PMID 39455728, 2024). "To investigate the role of CMTM3 in sepsis, we extracted the top 500 genes showing significant correlation with CMTM3 expression for further analysis." (PMID 39455728, 2024). "Here, we find that CMTM3 expression is elevated in sepsis and plays a crucial role in mediating the imbalance of neutrophil migration." (PMID 39455728, 2024). "Targeting CMTM3 thus could improve organ damage and survival rates in septic mice, thus potentially serving as a novel therapeutic target for the treatment of sepsis." (PMID 39455728, 2024). "Our research findings suggest that targeting CMTM3 could serve as a target to improve the imbalance of neutrophil migration in sepsis immunotherapy." (PMID 39455728, 2024). "Similarly, we further validated the protective effect of Cmtm3 knockout through the TLR4 pathway in a CLP-induced sepsis model." (PMID 39455728, 2024). "Therefore, exploring the precise function and mechanism of CMTM3 in sepsis is of great significance." (PMID 39455728, 2024). "Further research is needed to fully elucidate the role of CMTM3 in sepsis." (PMID 39455728, 2024). "Intriguingly, our study found higher CMTM3 expression in sepsis survivors, which may reflect an adaptive immune response that mitigates the severity of sepsis." (PMID 39455728, 2024). "Further research should address these gaps to fully understand the role of CMTM3 in sepsis." (PMID 39455728, 2024). "Moreover, Cmtm3 deletion was shown to decrease neutrophil mobilization from the bone marrow, likely due to the downregulation of cytokine release, highlighting CMTM3 as a potential target for anti-inflammatory therapy in sepsis." (PMID 39455728, 2024). "However, the precise role of CMTM3 in sepsis remains elusive, warranting further investigation." (PMID 39455728, 2024).
Sepsis (continued). "Cmtm3 KO reduced the release of TNF-α, IL-1β, and IL-10 in the peripheral blood of CLP-induced sepsis mice, while TLR4 overexpression reversed this protective effect." (PMID 39455728, 2024). "Our comprehensive bioinformatics analysis revealed that CMTM1-6 are upregulated in sepsis, with CMTM3 showing differential expression between survival and non-survival groups, suggesting a distinct role for CMTM3 in sepsis progression." (PMID 39455728, 2024). "In addition, future research should focus on elucidating the precise molecular mechanisms by which CMTM3 regulates TLR4 expression, to clarify its dual role in sepsis." (PMID 39455728, 2024).
testis tumors (1 paper, 2014). "We further analyzed the expression of CMTM3 in 20 paired testis tumor tissues and the corresponding benign adjacent tissues." (PMID 24586462, 2014). "We next performed the bisulfite sequencing of 53 CpG sites including the CMTM3 core promoter region (−353 to +126 bp from start the codon site) in 13 paired primary testis tumor samples." (PMID 24586462, 2014). "Two independent studies showed that CMTM3 expression was statistically significantly decreased in testicular tumors." (PMID 24586462, 2014). "The expression of CMTM3 in testicular tissues and a series of testis tumors." (PMID 24586462, 2014). "Of 75 cases of testis tumors, 36 (48%) cases of tumors showed no CMTM3 expression, 27 (36%) cases of tumors had low CMTM3 expression, and 12 (16%) cases of tumor had moderate CMTM3 expression." (PMID 24586462, 2014).
triple-negative breast carcinoma (1 paper, 2021). An invasive breast carcinoma which is negative for expression of estrogen receptor (ER), progesterone receptor (PR), and human epidermal growth factor receptor 2 (HER2). "In addition to CMTM6, our in silico data on triple negative breast cancer patients showed a positive correlation between EMT markers and two other members of CMTM family (CMTM3 and CMTM7)." (PMID 33803139, 2021).
urogenital cancer (1 paper, 2014). "To investigate CMTM3's role in urogenital cancer, we first queried the Oncomine database to assess the relative expression levels of CMTM3 in urogenital cancer." (PMID 24586462, 2014). "We also measured CMTM3 mRNA levels in 10 urogenital cancer cell lines." (PMID 24586462, 2014).